USP35 (ubiquitin specific peptidase 35)
Diseases named in the same sentence as USP35 in open-access papers (continued):
Sharing a sentence is not in itself a finding about the gene and the disease.
Parkinson disease (1 paper, 2023). A progressive degenerative disorder of the central nervous system characterized by loss of dopamine producing neurons in the substantia nigra and the presence of Lewy bodies in the substantia nigra and locus coeruleus. "Other deubiquitinating enzymes such as USP30 and USP35 have been implicated in Parkinson’s disease through their roles in regulating mitophagy." (PMID 38017009, 2023).
prostate tumors (1 paper, 2022). "Last of all, to further evaluate USP35 roles in prostate tumorigenesis, we generated an orthotopic prostate tumor model in which C4-2b cells were injected into the prostate gland of nude mice." (PMID 36357379, 2022). "In accordance to our speculations, USP35 overexpression could result in the formation of larger prostate tumors relative to those in control mice, suggesting that USP35 significantly promoted tumorigenesis." (PMID 36357379, 2022).
tumor (21 papers, 2010 to 2025). "In the current study, we found that the expression of USP35 was increased in GC tissues and was associated with nodal metastasis and tumor grade." (PMID 38250150, 2024). "Further analysis of TCGA dataset showed that USP35 expression was associated with H. pylori infection, nodal metastasis status, and GC tumor grade." (PMID 38250150, 2024). "As for the involvement of USP35 in cancer immunology, two studies indicated that USP35 overexpression was associated with immune-suppressive tumor microenvironment (TME), especially the decrease in CD8+ T cell infiltration." (PMID 36864055, 2023). "H460 and H1299 cells are epidermal growth factor receptor (EGFR) wild‐type cells and we further determined the role of USP35 on cell growth, ferroptosis induction, and tumor growth in EGFR mutated H1650 cells." (PMID 33931967, 2021). "Correspondingly, the tumor‐bearing mice inoculated with USP35‐deficient cancer cells had reduced tumor volumes and weights upon DDP or PTX treatment." (PMID 33931967, 2021). "Amplification of 8q24.11-13 (THRAP6, DCC1, SQLE, SPG8) and 11q14.1 (NDUFC2, ALG8, USP35) have been associated with poor prognosis in a novel subtype of high-grade ER- tumors." (PMID 20932292, 2010). "In addition, USP35 was positively associated with Snail1 expression in tumor cell lines and human GC tissues." (PMID 38250150, 2024). "Both DNA or RNA induction pathways stimulate the expression of type I interferons, and USP35 knockdown enhances anti-tumor immunity in response to the oncolytic virus therapy." (PMID 40016186, 2025). "Immunohistochemical analysis comparing the expression of USP35 in HCC tumors and peritumoral tissues revealed a significant upregulation of USP35 in tumor tissues." (PMID 40607251, 2025). "Compared with the control group, treatment with USP35 knockdown reduced the tumor standard uptake value (SUV)." (PMID 41372134, 2025). "Depletion of USP35 promotes ferroptosis and suppresses lung cancer cell growth and tumor progression." (PMID 40016186, 2025). "When mice were treated with cisplatin, USP35 knockdown significantly reduced the tumor weight and dissemination." (PMID 39678497, 2024). "In detail, the expression of USP35 was significantly increased in OC, and knockdown of USP35 reduced the tumor burden in mice." (PMID 39678497, 2024). "The results based on the analysis of TCGA and GEO datasets showed that the expression level of USP35 is correlated with tumor grade, node metastasis, and H. pylori infection." (PMID 38250150, 2024). "Recent works have suggested that USP35 is a promising cancer target due to its role in tumor growth and chemo-resistance by regulating the stability of important players in tumor development and cell death." (PMID 36864055, 2023). "We have demonstrated that USP35 controls tumor growth and chemotherapeutic vulnerability in CRC by mediating the stability of FUCA1, indicating that USP35 is an intriguing target in CRC." (PMID 36864055, 2023). "In this study, we highlighted the SREBP2-dependent MVA crosstalk is activated by USP35/BRFP1 axis to drive tumor progression." (PMID 36357379, 2022). "Our previous work has found that USP35 impedes tumor growth through inhibiting NF‐κB activation by stabilizing ABIN‐2." (PMID 34618999, 2022). "Taken together, these data identified FPN as a potential target of USP35 in modulating ferroptosis and tumor progression." (PMID 33931967, 2021). "The role of USP35 on ferroptosis and tumor progression were also tested in mouse tumor xenograft models in vivo." (PMID 33931967, 2021). "Data from the tumor‐xenografts experiment further indicated that USP35 silence suppressed tumor volumes and weights after 25‐day growth." (PMID 33931967, 2021). "USP35 silence further suppressed the growth, colony formation and tumor progression of H1650 cells upon GFB treatment." (PMID 33931967, 2021). "In line with the in vitro data, USP35‐overexpressed cells had decreased tumor volumes and weights after FPN knockdown." (PMID 33931967, 2021).
tumor (continued). "Collectively, the data indicate that USP35 overexpression blocks erastin/RSL3‐mediated tumor suppressive effects." (PMID 33931967, 2021). "In keeping with this scenario, ABIN-2 protein abundance in human tumor samples correlated well with USP35 abundance." (PMID 26348204, 2015). "USP35 overexpression inhibited cell proliferation in vitro and inhibited xenograft tumor growth in vivo." (PMID 26348204, 2015). "Collectively, the data presented here suggested that USP35, a member of DUBs family, exerts tumor-suppressive function and inhibits tumor growth which can be up-regulated by the miR let-7a in human cancers." (PMID 26348204, 2015). "Our findings not only provide a novel molecular insight into miR let-7a-mediated tumor suppression, but also implicate USP35 as a promising molecular target for cancer therapy for the first time." (PMID 26348204, 2015). "Given that oncolytic virus activates the RNA signaling pathway, we hypothesized that the knockdown of USP35 might enhance the anti-tumor immunity triggered by OVs." (PMID 40016186, 2025). "Compared with the control group, treatment with exosome USP35 promoted tumor dissemination." (PMID 41372134, 2025). "Since the RIG-I-MAVS pathway plays a key role in promoting anti-tumor T-cell infiltration, we next investigated whether USP35 regulates this signaling." (PMID 40016186, 2025). "Targeting USP35 may offer a new therapeutic strategy to enhance anti-tumor immunity in oncolytic virotherapy." (PMID 40016186, 2025). "This also suggests that USP35 may be involved in regulating the energy metabolism of GC cells and thus tumor progression, but whether it is involved in regulating the adhesion of tumor cells remains unclear." (PMID 41372134, 2025). "Furthermore, the expression levels of USP35 and Snail1 were highly correlated in different tumor cells and clinical GC tissues." (PMID 38250150, 2024). "Moreover, the density and proliferation of xenograft tumor cells were also reduced by USP35 knockdown as indicated by H&E staining and Ki-67 IHC results." (PMID 37993419, 2023). "Our present finding indicates that USP35 expression level could affect the fate of tumor cells when stressful stimuli are presented." (PMID 34618999, 2022). "Considering USP35 correlates tightly with tumor progression, whether USP35 could modulate other oncogenic features, like metabolic remodeling, stem-like properties is still unknown." (PMID 36357379, 2022). "Our previous study has implied that USP35 may function as a tumor suppressor for the reason that overexpression of USP35 inhibits cell proliferation." (PMID 34618999, 2022). "It remains to be determined whether this tumor-suppressor function of USP35 is the action of USP35iso2 or the cancer type-specific action of USP35." (PMID 34131114, 2021). "The enhanced tumor growth‐derived from USP35‐overexpressed cells was also inhibited by FPN silence." (PMID 33931967, 2021). "The tumor volumes and weights in nude mice were also unaffected by USP35 overexpression." (PMID 33931967, 2021). "IHC staining was performed to detect the expression of USP35, STING, HIF-1α, and ICAM1 in the tumor tissues, and the results were consistent with those obtained in vitro." (PMID 41372134, 2025). "On the other hand, exosome USP35 derived from GC cells induces MMT in PMCs, creating a “soil” for the tumor metastasis cascade." (PMID 41372134, 2025). "First of all, we queried the expression data of USP35 in GDS2545 derived from the Gene Expression Omnibus (GEO) database, observing that USP35 levels were higher in 65 tumor samples as compared to 63 adjacent normal tissues." (PMID 36357379, 2022). "When activated by miR let-7a, USP35 inhibits NF-κB activation by deubiquitinating and stabilizing ABIN-2, which subsequently inhibits tumor growth." (PMID 29449677, 2018).
tumor (continued). "Moreover, HCC cells elevate PKM2 expression by preventing its degradation, as ubiquitin-specific protease 35 (USP35) stabilizes PKM2 through deubiquitination, promoting aerobic glycolysis and tumor progression." (PMID 41169372, 2025). "Similarly, after sacrificing the mice, the combined use of USP35 knockdown and STING overexpression reversed the tumor dissemination promoted by the overexpression." (PMID 41372134, 2025). "At the same time, exosome USP35 derived from GC cells induces MMT in PMCs, induces the formation of peritoneal-specific PMNs, and creates favorable conditions for the attachment and growth of tumor cells in the peritoneum." (PMID 41372134, 2025). "Whether USP35 can disrupt the PMC barrier through the exosome pathway, thereby facilitating the attachment and growth of tumor cells, remains to be further explored." (PMID 41372134, 2025). "The mRNA expression level of USP35 was significantly increased after anti-PD-1 or anti-CTLA-4 treatment compared with IgG treatment, suggesting USP35 may play a role in tumor immunity." (PMID 40016186, 2025). "Further investigation revealed that USP35 removed the ubiquitin chains from stimulator of interferon gene (STING) to attenuate interferon signaling, thereby reducing the cisplatin-induced anti-tumor responses." (PMID 39678497, 2024). "In summary, these results suggest that USP35 may promote HCC development by stabilizing ABHD17C, thereby facilitating tumor progress through the activation of the PI3K/AKT signal cascade." (PMID 37993419, 2023). "Especially, there is no tumor formation in two mice injected with USP35-transfected cells at the end of the observation period." (PMID 26348204, 2015). "Then, we showed that USP35 expression was decreased dramatically in the tumor tissues compared with the adjacent non-cancerous tissues." (PMID 26348204, 2015). "However, the role of USP35 in EMT and tumor metastasis remains unclear." (PMID 38250150, 2024). "Both USP35 and RRBP1 expression levels were significantly higher in more advanced TNM stages, but were not significantly affected by sex, age, or tumor size." (PMID 34618999, 2022). "However, the role of USP35 in EMT and tumor metastasis has not yet been reported." (PMID 38250150, 2024).
cancer (16 papers, 2014 to 2026). A tumor composed of atypical neoplastic, often pleomorphic cells that invade other tissues. "Apart from the cell death-associated role of USP35, two other aspects of USP35 seem to be very intriguing to us as well—its participation in mitosis and cancer immunology." (PMID 36864055, 2023). "Two studies demonstrated that USP35 deficiency sensitized cancer cells to cisplatin (the first platinum anti-cancer drug) treatment via de-stabilizing anti-apoptotic factor BIRC3 or activating cGAS-STING-TBK1-mediated expression of type I interferons." (PMID 36864055, 2023). "Given the underlying roles of USP35 in cancers and the gap of current knowledge of this molecule, we aim to understand the biological functions of USP35, specifically in NSCLC." (PMID 34618999, 2022). "Moreover, the TCGA data also suggested that high expression of USP35 was associated with increased cancer mutational in CRC patients and higher recurrence rate in CRC patients receiving postoperative chemotherapy." (PMID 36864055, 2023). "Nevertheless, additional research is needed to fully understand the relationship between the deubiquitinase USP35 and cancer chemotherapy." (PMID 39156988, 2024). "Despite the limited studies exploring the functions of USP35 in cancers, recent evidence has suggested that USP35 is a potential cancer target that regulates tumorigenesis, cell death, and cancer immunology." (PMID 36864055, 2023). "The mitotic role of USP35 places it in an appealing spot for targeting, considering that mitosis is a promising anti-cancer target." (PMID 36864055, 2023). "It was not until recent years that the role of ubiquitin‐specific‐processing protease 35 (USP35) in cancers began to be understood." (PMID 34618999, 2022). "Recently, emerging evidence suggests that USP35 is involved in cell cycle regulation, cell fate, and cancer development." (PMID 34618999, 2022). "We further demonstrated that USP35 enhanced cancer cell growth, migration ability and stem-like properties in vitro and in vivo." (PMID 36357379, 2022). "Particularly, FPN protein abundances in cell membrane were increased in cancer cells with USP35 overexpression, but decreased by USP35 knockdown." (PMID 33931967, 2021). "USP35 expression is frequently decreased in human cancer tissues when compared with adjacent normal tissues." (PMID 26348204, 2015). "Overexpression of USP35 significantly inhibited the tumorigenic potential of cancer cells in nude mice." (PMID 26348204, 2015). "Overall, our study provides a novel rationale of targeting miR let-7a-USP35-ABIN-2 pathway for the therapy of cancer patients." (PMID 26348204, 2015). "In this study, we first show that USP35 has clinical significance and plays a functional role in human cancers." (PMID 26348204, 2015). "Consistent with the qRT-PCR results, the protein level of USP35 was also significantly decreased in the cancer tissues compared with the adjacent normal tissues." (PMID 26348204, 2015). "Ectopic USP35 expression in cancer cells inhibited cell proliferation, while silencing USP35 induced proliferation in vitro." (PMID 26348204, 2015). "Among the genes whose expression was altered by changing the level of miR let-7a, USP35 was first identified and validated with further qRT-PCR and Western blot in different cancer cell lines." (PMID 26348204, 2015). "Taking together, these results suggested that USP35 is an inhibitor of proliferation in cancer cells both in vitro and in vivo." (PMID 26348204, 2015). "Consistent with our findings from the microarray analysis, USP35 expression was positively correlated with miR let-7a expression in human cancer tissues." (PMID 26348204, 2015). "Here, we first identified miR let-7a as a positive regulator of USP35 expression and showed that USP35 expression positively correlates with miR let-7a expression in different cancer cell lines and tissues." (PMID 26348204, 2015).
cancer (continued). "Notably, the upregulation of USP35 in various cancers implies a potential relationship between USP35 and NRF2 in the context of resistance to chemotherapeutic agents." (PMID 39156988, 2024). "This study adds another evidence for USP35-targeted therapy in cancer." (PMID 36864055, 2023). "Considering the previously reported role of FUCA1 in cancer growth and chemo-resistance, we here investigated whether the influence of USP35 on cell proliferation and drug resistance was mediated or partially mediated by FUCA1 in our study." (PMID 36864055, 2023). "The previous studies have connected USP35 to immune microenvironment to some levels, and future studies may shed more light on whether and how targeting USP35 will activate the immune system against cancers in different models." (PMID 36864055, 2023). "Given that current studies have connected USP35 to therapeutic sensitivity in a few types of cancers, it’s worth investigating whether USP35 is a universal regulator of chemo-sensitivity in other types of cancers." (PMID 36864055, 2023). "The oncogenic function of USP35 in other cancers has been well characterized." (PMID 37993419, 2023). "Specific roles in different cancer types and detailed mechanisms of USP35 need to be delineated." (PMID 34618999, 2022). "Recently, USP35 is emerging as a hotspot target in cancer research." (PMID 36357379, 2022). "Besides, HETEs levels were increased in erastin and RLS3‐treated cancer cells, but were decreased in those with USP35 overexpression except 12‐HETE." (PMID 33931967, 2021). "To extend our in vitro observations, we investigated whether USP35 could regulate tumorigenic capacity of cancer cells in vivo." (PMID 26348204, 2015). "So we speculate that USP35 can inhibit cancer cell growth through inhibiting NF-κB pathway by stabilizing ABIN-2." (PMID 26348204, 2015). "Therefore, the upregulation of USP35 may be the restriction mechanism of STING activity in cancer cells." (PMID 38525112, 2024). "Their study also raises a question whether targeting USP35 will modulate Taxol response in cancers." (PMID 36864055, 2023). "USP35, USP36, USP37, USP47, USP49, and OTUD6B play crucial roles in cancer progression and chemoresistance across various cancers, including NSCLC." (PMID 41399373, 2026). "In cancer cells, activated STING promotes its binding with USP35 in a manner dependent on the phosphorylation of STING." (PMID 38525112, 2024). "Secondly, exosome USP35 derived from GC cells has been shown to promote the mesothelial–mesenchymal transformation (MMT) of PMCs, preparing the “soil” for cancer cell adhesion and growth and contributing to the establishment of a pre-peritoneal-metastasis adaptive microenvironment." (PMID 41372134, 2025). "Among these potential targets of USP35, we would like to specifically focus on α-L-fucosidase 1 (FUCA1) in our current study, considering the strong relevance of altered glycosylation in cancer development and therapeutics." (PMID 36864055, 2023). "We next examined let-7a and USP35 expression in a panel of 10 human cancer cell lines and their corresponding non-malignant cell lines." (PMID 26348204, 2015). "Subsequently, we presented a serial evidence to show that USP35 could deubiquitinate and stabilize ABIN-2 in cancer cells." (PMID 26348204, 2015). "Our current findings identify a regulatory network of miR let-7a-USP35-ABIN-2 pathway, which may serve as potential therapeutic targets to help us control the human cancer progression." (PMID 26348204, 2015). "To explore any clinical significance of the observation, we analyzed the expression of USP35 and miR let-7a in human cancer tissues and the corresponding non-cancerous normal tissues as indicated." (PMID 26348204, 2015).
infection (3 papers, 2021 to 2025). The state of being infected such as from the introduction of a foreign agent such as serum, vaccine, antigenic substance or organism. "In summary, we identified the deubiquitinase USP35 as a host factor modulating MAVS activity during the infection of RNA viruses." (PMID 40016186, 2025). "Infection with H. pylori increased USP35 and Snail1 protein levels, indicating that H. pylori infection contributes to the upregulation of USP35 and Snail1." (PMID 38250150, 2024).
USP35 also shares sentences with these, for which no sentence is quoted: gynecological cancers (1 paper); liver cancer (1).